AHRR (aryl hydrocarbon receptor repressor)
Diseases named in the same sentence as AHRR in open-access papers (continued):
Sharing a sentence is not in itself a finding about the gene and the disease.
Obesity (6 papers, 2016 to 2026). Accumulation of substantial excess body fat. "While cg05575921 AHRR provided valuable insights into smoking history, other DNAm markers related to cardiometabolic risk factors (e.g., diabetes, obesity, hypertension) will require further validation to determine their independent predictive value." (PMID 41446364, 2026). "For those 12 genes, six of them (DDO, SEPT9, TMEM45B, RXRα, ZNF395 and AHRR) were previously reported to be implicated in the obesity or related diseases and the rest six were novel (PACRG, LINC00494, KLHL4, DTX1, VCX3A and VSTM1)." (PMID 35568907, 2022). "Through simultaneously measuring methylation at AHRR as well as a panel of other loci linked to important health outcomes, such as diabetes and obesity, it may well be that patients will gain additional motivation to collaborate with their healthcare providers in optimizing their well-being." (PMID 27092088, 2016). "Birth weight was also associated with AHRR (involved in cell growth and differentiation), HFI3A (obesity-associated gene) and LEP (appetite-related) methylation." (PMID 30096154, 2018).
coronary heart disease (5 papers, 2016 to 2023). "Several of these hits including cg18181703 (SOCS3), cg06126421 (TUBB), and cg05575921 (AHRR) were associated with future incidence of coronary heart disease and smoking, whereas two other CpGs were recently identified in an EWAS of type 2 diabetes." (PMID 31205673, 2019). "Four of them (CLDND1: Claudin Domain Containing 1, AHRR: Aryl Hydrocarbon Receptor Repressor, MPO: Myeloperoxidase, and PTCD2: Pentatricopeptide Repeat Domain 2), involved in lipid metabolism and inflammatory diseases, were associated with coronary heart disease." (PMID 37190071, 2023). "Follow-up studies also suggested AHRR methylation in blood as a biomarker for cardiovascular disease in the Caucasian population, such as myocardial infarction, ischemic heart disease, ischemic stroke, and heart failure, as well as a predictor of the risk of all-cause mortality." (PMID 35964014, 2022).
lung diseases (5 papers, 2014 to 2023). "Future studies may address the additional value of AHRR methylation recovery in predicting risks of pulmonary diseases." (PMID 36621758, 2023). "Further studies are needed to investigate the role of the AHRR gene in lung disease beyond smoking." (PMID 35681244, 2022). "To explore the effects of gene expression of CHRNA5, AMICA1, and AHRR on lung diseases, we conducted MR using expression of these three genes as the exposure, cis eQTLs of these genes from FHS whole blood as the instrumental variables, and lung disease traits as the outcomes." (PMID 33752734, 2021). "The mechanisms linking hypomethylation, smoking, and lung disease are not well described, but inflammatory processes may be implicated as AHRR hypomethylation is associated with the activation of natural killer cells." (PMID 36621758, 2023). "The role of MMP12, SPP1, AHRR and CYP1B1 in cigarette smoke-related lung diseases have been well described and studied." (PMID 24663285, 2014).
ovarian carcinoma (5 papers, 2012 to 2024). A malignant neoplasm originating from the surface ovarian epithelium. "Moreover, the loss of AhRR correlates with an aggressive tumorigenic phenotype in several tumors including colon, cervical, and ovarian carcinoma." (PMID 39200369, 2024). "A deeper database analysis of genes involved in copy number gains revealed three genes whose expression negatively correlates with ovarian cancer patients’ overall survival in all tested datasets: AhRR, GALNT10, and PPP1R3C." (PMID 37511212, 2023). "Previously, statistics have shown a consistent downregulation of AHRR throughout many types of tumors, including colon, breast, lung, cervical, and ovarian cancer, when compared with normal tissues of the same anatomical origin." (PMID 22952704, 2012). "AhRR hypermethylation seems to also occur in other cancer conditions, including ovarian cancer; however, our databases analyses reported different AhRR expression levels in ovarian cancer samples, and a correlation between higher AhRR expression levels and patients’ prognoses." (PMID 37511212, 2023). "Furthermore, it has been previously reported that higher cancer stemness marker expressions were related to worse PFS in ovarian cancer patients, thus strengthening the potential for AhRR and PPP1R3C involvement in cancer stem cell regulation." (PMID 37511212, 2023). "However, since the role of GALNT10 in ovarian cancer had already been reported, we focused our attention on AhRR and PPP1R3C." (PMID 37511212, 2023). "Taken together, our functional investigations further support a tumour-suppressive role of AHRR and an oncogenic function of SFRP2 in ovarian epithelial cancer." (PMID 38361045, 2024). "Bioinformatic analyses of genes involved in copy number gains revealed that AhRR and PPP1R3C expression negatively correlated with ovarian cancer patients’ overall and progression-free survival." (PMID 37511212, 2023). "In conclusion, we reported for the first time, to the best of our knowledge, the prognostic role of AhRR and PPP1R3C expression in serous ovarian cancer, and their correlation with ovarian cancer stem cell markers." (PMID 37511212, 2023). "On top of that, the positive correlation between AhRR and PPP1R3C expression and ovarian cancer stemness markers’ expressions suggest a potential role in cancer stem cells, and reinforces their use as prognostic markers." (PMID 37511212, 2023). "We also demonstrated that increased AhRR and PPP1R3C expression was maintained in some CSCs subpopulations, suggesting their possible role in ovarian cancer." (PMID 37511212, 2023). "To better analyze AhRR and PPP1R3C’s role in treatment responses, we investigated whether AhRR and PPP1R3C expression also correlates with ovarian cancer patients’ progression-free survival (PFS)." (PMID 37511212, 2023). "Interestingly, AhRR and PPP1R3C expression significantly correlates with stemness markers’ (ALDH1A1, CD44, ABCG2, NANOG) expressions in ovarian cancer tissues (p < 0.01)." (PMID 37511212, 2023). "Altogether, these data may suggest a potential prognostic role of AhRR and PPP1R3C, independent from chemotherapy treatment, in ovarian cancer." (PMID 37511212, 2023). "Furthermore, AhRR and PPP1R3C’s increased expression was maintained in some CSC subpopulations, reinforcing their potential role in ovarian cancer." (PMID 37511212, 2023).
asthma (4 papers, 2019 to 2026). "DNA methylation at CpG locus cg05575921 on the AHRR gene resulted in the strongest association with asthma status in magnitude, with a 1% increase in methylation levels corresponding to an odds ratio (OR) of 0.90 (95% CI = 0.85, 0.96)." (PMID 31342008, 2019). "Associations between DNA methylation at selected AHRR loci (mediators) and self-reported maternal smoking (exposure) from a model for the mediator, as well as associations between DNA methylation and asthma status (outcome) from a model for the outcome." (PMID 31342008, 2019). "Our data showed that AHRR expression tended to be decreased in asthma while it was increased in the COPD triple co-cultured epithelium after UPM exposure." (PMID 36012391, 2022). "We observed associations between DNA methylation levels at the cg05575921 CpG locus on the AHRR gene and asthma status." (PMID 31342008, 2019). "Self-reported maternal smoking was associated with a −1.5% (95% confidence interval (CI) = −2.4%, −0.6%) lower methylation at CpG locus cg05575921 on the AHRR gene; a 1% increase in DNA methylation at the same locus resulted in an odds ratio (OR) of 0.90 (95% CI = 0.83, 0.96) for the odds of asthma." (PMID 31342008, 2019). "Our results are consistent with the hypothesis that DNA methylation is a potential biologic mediator of the harmful effects of in utero tobacco smoke exposures on asthma and asthma-related outcomes, particularly with respect to methylation at the AHRR gene." (PMID 31342008, 2019). "Eligible studies included pediatric populations with asthma or wheeze phenotypes assessing predefined genetic (ORMDL3, GSDMB) or epigenetic (AHRR, FOXP3, CpG loci) markers and reporting odds ratios (ORs) or sufficient data for their derivation." (PMID 41682911, 2026).
chronic obstructive pulmonary disease (4 papers, 2021 to 2025). A chronic and progressive lung disorder characterized by the loss of elasticity of the bronchial tree and the air sacs, destruction of the air sacs wall, thickening of the bronchial wall, and mucous accumulation in the bronchial tree. "We investigated whether AHRR DNA methylation is related to chronic obstructive pulmonary disease (COPD) and studied its function in airway epithelial cells (AECs)." (PMID 36359818, 2022).
colitis (4 papers, 2016 to 2024). Inflammation of the colon. "In comparison with AhR ligand-deprived diets, dietary I3C supplementation drives the expression of the AhR repressor (AhRR) in intestinal immune cells of AhRR-reporter mice, strengthens intestinal barrier integrity, and lowers susceptibility to colitis." (PMID 34966278, 2021). "Our finding that genetic deficiency of either AhR or AhRR exacerbates intestinal inflammation in the DSS colitis model at first glance questions the inhibitory action of the AhRR on AhR activity." (PMID 27184933, 2016). "Taken together, AhRR-deficiency was found to cause enhanced susceptibility to DSS colitis similar to AhR-deficiency." (PMID 27184933, 2016). "On the other hand, when assessing its role in a gut-associated inflammatory response, AhRR deficiency aggravated symptoms of colitis similar to deficiency of the AhR itself." (PMID 27184933, 2016). "Interestingly both, AhR and AhRR-deficient mice are highly susceptible to DSS-induced colitis, which is likely due to the highly cell type specific expression of the AhRR and the resulting cell type-specific differences in AhR/AhRR signalling." (PMID 32366032, 2020). "In this study, we analyzed the influence of dietary AhR ligands on AhRR expression, colitis pathology, and changes in the microbiome." (PMID 32366032, 2020). "Although the impact of AhRR deficiency on IEL was more subtle, we also detected a 50% reduction of colonic TCRγδ+ IEL in AhRRE/E mice, which may contribute to the enhanced susceptibility of these mice to development of colitis." (PMID 27184933, 2016).
diabetes (3 papers, 2016 to 2026). "Our results showed no or very weak 6p21.33 and AHRR methylation difference among people with the variant status of hypertension and diabetes, and people with different levels of TC, TG, HDL, and LDL." (PMID 35964014, 2022). "It seems that the blood-based 6p21.33 and AHRR methylations were not influenced by hypertension, diabetes, levels of TC, TG, HDL, and LDL." (PMID 35964014, 2022).
lung adenocarcinoma (3 papers, 2019 to 2024). A carcinoma that arises from the lung and is characterized by the presence of malignant glandular epithelial cells. "In addition, we also analyzed the associations between a total of seven isoforms of AHRR and DNA methylations at CpG sites in lung adenocarcinoma tumor tissues." (PMID 32928150, 2020). "Additional evidence showed that the elevated expression of AHRR and GPR15 were associated with smoking-altered hypomethylations at cg14817490 and cg19859270, respectively, in lung adenocarcinoma tumor tissues." (PMID 32928150, 2020). "In lung adenocarcinoma, our results showed that smoking increased the expression of three genes, AHRR, GPR15, and HDGF, and decreased the expression of two genes, CAPN8, and RPS6KA1, which were consequently associated with increased smoking-related mutational signature." (PMID 32928150, 2020). "However, findings from MR analysis were corroborated by the lack of evidence for differential methylation at AHRR between lung adenocarcinoma tissue and adjacent healthy tissue, and weak evidence for hypermethylation (opposite to the expected direction) in squamous cell lung cancer tissue." (PMID 31549173, 2019).
male infertility (3 papers, 2019 to 2022). The inability of the male to effect fertilization of an ovum after a specified period of unprotected intercourse. "AHRR has been implicated in lung function decline and male infertility, two conditions associated with prenatal nicotine exposure." (PMID 33419350, 2020). "AHRR encodes a component in the aryl hydrocarbon receptor signaling cascade, which is involved in cell growth, and mutations in AHRR have been shown to associate with male infertility." (PMID 31494266, 2019).
serous ovarian cancer (3 papers, 2023 to 2024). "Remarkably, we identified a potential prognostic role of AhRR and PPP1R3C in serous ovarian cancer by bioinformatics analyses of array-CGH data performed on these CSCs." (PMID 39596687, 2024). "In conclusion, we reported for the first time, to the best of our knowledge, a prognostic role of AhRR and PPP1R3C expression in serous ovarian cancer." (PMID 37511212, 2023). "In a previous work, we identified a potential prognostic role of AhRR and PPP1R3C expression in serous ovarian cancer, starting from a detailed bioinformatics analysis of copy number gain arising in CSCs by array comparative genomic hybridization (array-CGH) analysis." (PMID 39596687, 2024).
autoimmune disease (2 papers, 2022). A disorder resulting from loss of function or tissue destruction of an organ or multiple organs, arising from humoral or cellular immune responses of the individual to their own tissue constituents. "Thus, blocking the AhRR and Erα can potentially reestablish immune homeostasis in autoimmune diseases and other immune-mediated diseases." (PMID 36601108, 2022).
breast tumors (2 papers, 2018 to 2020). "Notably, our results revealed, for the first time, that breast tumors with high AHRR mRNA levels were significantly associated with good metastasis-free survival, compared to tumors expressing low AHRR mRNA levels." (PMID 29320557, 2018). "AHRR mRNA level was significantly twofold higher in high AHR-expressing breast tumors compared to low AHR-expressing tumors, but only in the ERα-negative subpopulation (p = 0.0036)." (PMID 29320557, 2018). "In fact, a recent study in a cohort of 439 breast tumors showed that high AHR expression correlated with the up-regulation of genes involved in inflammation, metabolism, invasion and growth factor signaling while high AHRR mRNA levels correlated with good-metastasis free survival." (PMID 32286485, 2020). "In a series of 439 ERα-positive or ERα-negative breast tumors, representing the different molecular subtypes, large ranges of AHR (0–5.8-fold difference) and AHRR (0–19.8-fold difference) mRNA expression were observed, reflecting extensive heterogeneity of gene expression in tumor samples." (PMID 29320557, 2018).
colon carcinoma (2 papers, 2012 to 2023). "Moreover, AhRR overexpression in colon cancer leads to cell proliferation and altered cell adhesion, thus enhancing metastatic properties." (PMID 37511212, 2023).
colorectal cancer (2 papers, 2023 to 2025). A primary or metastatic malignant neoplasm that affects the colon or rectum. "Previous research has shown that the expression of the AHRR gene in human colorectal cancer tissue correlates with CD40/CD40L signaling and histological grade." (PMID 40611182, 2025). "Among the mutated genes in the adenomatous tissue samples involved in our study, PCDHGB4, AHRR, KIF4, LPAR6, NBPF1, and NCEH1 were already associated with colorectal cancer formation, while ANKRD30A, ITIH1, and KIAA0556 were related to other types of cancers." (PMID 36765865, 2023).
lymphoma (2 papers, 2019 to 2021). A malignant (clonal) proliferation of B- lymphocytes or T- lymphocytes which involves the lymph nodes, bone marrow and/or extranodal sites. "This builds on our prior study in which we demonstrated that growth of lymphoma cells was suppressed in AhRR Tg mice." (PMID 33763068, 2021). "In order to test if AhRR suppresses inflammation-dependent tumor growth we treated mice with LPS after subcutaneous injection of EL4 lymphoma cells." (PMID 31035533, 2019). "Furthermore, inflammatory conditions induced by LPS stimulated tumor growth of EL4 lymphoma cells in wt mice, which was also suppressed in AhRR Tg mice indicating that AhRR may suppress tumor growth independent of exogenous and toxic AhR ligands." (PMID 31035533, 2019). "The results indicate a significantly suppressed tumor growth of EL4 lymphoma in AhRR Tg mice compared to wt B6 mice with or without TCDD treatment." (PMID 31035533, 2019). "In a transgenic mouse that overexpresses AhRR (AhRR Tg) we discovered that these mice suppress 2,3,7,8-tetrachlorodibenzo-p-dioxin (TCDD)- and inflammation-induced tumor growth after subcutaneous challenge of EL4 lymphoma cells." (PMID 31035533, 2019). "In summary, our data indicate that the tumor suppressive function of AhRR is mediated via its interaction with the non-canonical AhR pathway resulting in down-regulation of cellular inflammation through inhibition of the PKA-C/EBPβ inflammatory axis and inhibition of tumor growth and lymphoma." (PMID 31035533, 2019).
nicotine addiction (2 papers, 2019 to 2021). "This study aimed to evaluate the DNA methylation levels of cg05575921 (AHRR) and cg23771366 (PRSS23) and their correlation with lung function variables, cigarette consumption, and nicotine addiction in the Mexican smoking population." (PMID 34440450, 2021). "This study aimed to evaluate the DNA methylation level of cg05575921 (AHRR) and cg23771366 (PRSS23) and their correlation with lung function variables, cigarette consumption, and nicotine addiction in the Mexican smoking population." (PMID 34440450, 2021).
oral cancer (2 papers, 2019 to 2023). "In the analysis corresponding to oral-cancer patients, we found AHRR differentially hypomethylated cancer patients, but also in subjects without oral cancer in the targeted analyses." (PMID 37509437, 2023).
post-traumatic stress disorder (2 papers, 2023). An anxiety disorder precipitated by an experience of intense fear or horror while exposed to a traumatic (especially life-threatening) event. "In adults, decreased blood methylation of AHRR, in particular on cg26703534, has been associated with post-traumatic stress disorder cases." (PMID 37511531, 2023).
schizophrenia (2 papers, 2021 to 2025). A major psychotic disorder characterized by abnormalities in the perception or expression of reality. "The only probe found to be significantly associated with schizophrenia in the MOMENT MWAS was cg05575921 (annotated to AHRR; p = 2.79 × 10−27), a well-replicated DMP that has been previously associated with cigarette smoking." (PMID 33771206, 2021).
Stroke (2 papers, 2021 to 2023). Sudden impairment of blood flow to a part of the brain due to occlusion or rupture of an artery to the brain. "Furthermore, DNA methylation of AHRR gene might be implicated in the causal pathway between smoking, cIMT and stroke." (PMID 34091768, 2021).
autoimmune hepatitis (1 paper, 2024). Hepatitis caused by autoantibodies. "High expression of AHRR (AHR repressor) and HIF-1α inhibits AHR signaling in Th17 cells and regulatory T cells (Tregs) in autoimmune hepatitis (AIH)." (PMID 37692495, 2024).
bladder cancer (1 paper, 2018). "Hypomethylation of AHRR at cg05575921 has been linked to recent exposure to second–hand smoke, while others have reported significant associations between second–hand smoke exposure and differential DNA methylation in bladder cancer." (PMID 30389506, 2018).
chronic bronchitis (1 paper, 2019). A type of chronic obstructive pulmonary disease characterized by chronic inflammation in the bronchial tree that results in edema, mucus production, obstruction, and reduced airflow to and from the lung alveoli. "Methylation of AHRR cg05575921 was previously associated with lung function and chronic bronchitis in never-smokers." (PMID 31073081, 2019).